FLT3 (fms related receptor tyrosine kinase 3)
Diseases named in the same sentence as FLT3 in open-access papers (continued):
Sharing a sentence is not in itself a finding about the gene and the disease.
tumor (continued). "For example, EVs’ FLT3-ITD and NPM1 mRNAs serve for determining AML prognosis; FLT3-ITD, IGF-IR, and CXCR4 mRNAs help in AML treatment, whereas IGF-IR, CXCR4, and MMP4 mRNAs aid in understanding the behavior of the tumor niche." (PMID 37371477, 2023). "It functions by inhibiting the growth of tumor cells and the formation of blood vessels through targeting various serine/threonine and tyrosine kinases such as RAF1, BRAF, VEGFR 1, 2, 3, PDGFR, KIT, FLT3, FGFR1, and RET." (PMID 37299411, 2023). "Additionally, NK cells directly attract cDC1 accumulation inside the tumor lesion by XCL1 and CCL5 chemokines and promote their differentiation under the release of Flt3 factor with a strong inhibition of this axis induced by PGE2 tumor secretion." (PMID 36230990, 2022). "After 1 week when leukaemic bioluminescent signals became detectable, the tumour‐bearing mice were treated with FLT3‐ITD ASO‐loaded RBCEVs or negative control (NC) ASO‐loaded RBCEVs systemically (i.v.)every two days." (PMID 35851970, 2022). "Autophagy appears to mediates both pro-tumor and antitumor effects relevant to FLT3-ITD + AML cell proliferation under basal conditions, and its function in treatment resistance to FLT3 therapy is unclear." (PMID 35999260, 2022). "In contrast, other pathways prominently change their information flow at PBMC or normal as compared to tumor tissue: (i) turn off (BAG), (ii) decrease (such as BAFF, FLT3, and IL1), (iii) turn on (such as GAS and LIGHT), or (iv) increase (such as MIF, PARs, ANNEXIN, and IL16)." (PMID 35812372, 2022). "The combination of Dox and Cur had a synergistic effect and could improve Dox anti-tumor activity in AML cells, particularly leukemic stem cells, by inhibiting cell proliferation through FLT-3 protein suppression." (PMID 34641328, 2021). "Four ferroptosis driver genes FLT3, ALOX12B, ALOX15, and VDAC2, had a low CNV, and four ferroptosis suppressor genes ACSL3, CISD1, FANCD2, and SLC3A2, had a high CNV, indicating that ferroptosis was inhibited in tumor development." (PMID 34434214, 2021). "MerTK/FLT3-specific small molecule inhibitors UNC2025, MRX2843 and UNC1666 were shown to have significant effect on tumor growth of AML, ALL and melanoma in cell lines, murine models and primary patient tumor samples." (PMID 33801886, 2021). "Finally, treatment with 10 mg/kg LT-171-861 every other day for 16 days inhibited tumor growth in subcutaneous xenograft models with BaF3 cells transfected with FLT3-ITD-N676D (left) and FLT3-ITD-F691L (right)." (PMID 33391463, 2021). "Interestingly, STMN1 and ANGPT2 were significantly positively correlated with tumor purity, whereas RAP1A, FLT3, HSPA8, and PGF were all significantly negatively correlated with tumor purity." (PMID 34178637, 2021). "Known alternative lestaurtinib targets including Trk and FLT3 were not expressed in tumor cells we studied." (PMID 34400618, 2021). "Likewise, circMYBL2 promotes FLT3 kinase translation by strengthening the binding of PTBP1 to FLT3 mRNA, which regulates FLT3 kinase level and activation of FLT3-ITD-dependent tumor signaling pathways." (PMID 34445958, 2021). "In addition, nintedanib was recently shown to exert direct anti-tumor effect on tumor cells, but only those with oncogene addiction to growth factors receptors targeted by nintedanib, such as PDGFRα, FGFR2, FLT3, or RET." (PMID 32133285, 2020). "Sorafenib is a multikinase inhibitor that blocks several targets including Fms-like tyrosine kinase-3 (FLT3), platelet-derived growth factor (PDGF), vascular endothelial growth factor (VEGF), c-Kit and B-RAF signaling in both tumor cells and the surrounding endothelial cells." (PMID 32013003, 2020).
tumor (continued). "Moreover, we detected eight gene amplifications in six different tumor specimens, including CCND2 (n = 3), FLT3 (n = 3), FGFR1, and MYC." (PMID 33322358, 2020). "When quizartinib was administered to mice bearing FLT3-ITD mutated tumors, AC886 was rapidly detected and tumor regression was observed at doses of ≥1 mg/kg without severe body weight loss." (PMID 32215183, 2020). "The combination of venetoclax and quizartinib, a small molecular oral FLT3-tyrosine kinase inhibitor (TKI), induced tumor regression in FLT3-mutant AML cell lines that was more durable than with either agent alone, preventing tumor re‐emergence for up to 3 months following cessation of therapy." (PMID 33251134, 2020). "Interestingly, plasma FL concentrations in FL-expressing tumor xenograft models on day 22 were similar to those observed in AML patients treated with chemotherapy and FLT3 inhibitor." (PMID 31692922, 2019). "We performed whole-exome sequencing (WES) of tumor-normal matched samples of de novo AML-NK patients lacking mutations in NPM1, CEBPA or FLT3-ITD to identify new gene mutations with potential prognostic and therapeutic relevance to patients with AML." (PMID 30303964, 2018). "The same tumor had a FLT3-ITD but we did not detect any SV junctions in the matched normal in spite of the ITD having a higher tumor MAF (due to chromosome 13 LOH) than the fusion." (PMID 30262806, 2018). "Thus, targeting FLT3-PIM axis in AML is a promising, rational strategy to deplete these tumor-driving signals, increase the cytotoxicity of conventional chemotherapeutics, and improve clinical outcome of AML patients." (PMID 29682194, 2018). "More recently, single cell analysis demonstrated the existence of FLT3-ITD negative cells in clinically determined FLT3-ITD positive patients indicated the intra-tumor heterogeneity." (PMID 29262547, 2017). "Average tumor weight was reduced by 70% in mice injected with cells expressing FLT3-ITD-Y842F compared to mice injected with FLT3-ITD expressing cells, suggesting that the phosphorylation of the activation loop tyrosine is an important event in FLT3-ITD-mediated transformation." (PMID 28271164, 2017). "In two PDC cell lines with FLT3 amplification, FLT3 mRNA expression was increased, however, the growth of tumor cells was not significantly inhibited by either regorafenib or sorafenib which is known to block the activity FLT3." (PMID 27906677, 2017). "Furthermore, in nude mice xenografted with Ba/F3 cells expressing either FLT3-ITD, FLT3-D835Y, or FLT3-ITD-D835Y, gilteritinib showed antitumor efficacy at 10 mg/kg and 30 mg/kg, and induced tumor regression at 30 mg/kg, in all three models." (PMID 28516360, 2017). "However, due to digestive and cutaneous adverse effects and tumor stagnation, sorafenib was replaced with sunitinib (Sutent®), another TKI (VEGFR, PDGFR, Kit, FLT3)." (PMID 28420393, 2017). "In two PDC cell lines with FLT3 amplification, with increased FLT3 mRNA expression, tumor growths were not significantly inhibited by either regorafenib or sorafenib." (PMID 27906677, 2017). "In addition an inhibition of mast/stem cell growth factor (KIT), FMS-like tyrosine kinase 3 (FLT-3), TIE-2 (TEK tyrosine kinase, endothelial), tropomyosin-related kinase B (TRKB), and AXL lead to tumor regression." (PMID 27881963, 2016). "In addition, other groups have noted heterogeneity in the phosphorylation status of all three of these molecules (in both Mer and/or Flt3-ITD dependent cell lines) depending on the cell line, tumor type, assay, and/or in vitro therapeutic intervention." (PMID 25762638, 2015). "In conclusion, results from this study demonstrate that BPR1J-340 exhibits high potency and excellent selectivity against FLT3 kinase, strong suppression of the FLT3-ITD survival signaling pathway, favorable pharmacokinetic properties, and complete tumor regression in a FLT3-ITD+ xenograft model." (PMID 24416160, 2014).
tumor (continued). "However, measurable immune responses and control of tumor growth were achieved only by an adoptive transfer of antigen-specific transgenic T cells and co-administration of anti-CD40, Flt3, GMCSF and/or CpG." (PMID 21379572, 2011). "However, results of in vitro studies have since shown that sorafenib is a potent multikinase inhibitor, which also targets receptor tyrosine kinases associated with tumour angiogenesis (VEGFR-2, VEGFR-3, PDGFR-β) and tumour progression (c-KIT, FLT-3)." (PMID 16880785, 2006). "Notably, complete tumor regressions were observed in all mice treated with the combination of IHCH9033 with FLT3is, further underscoring the potential of this combination therapy in addressing FLT3-ITD AML." (PMID 39955584, 2025). "Additionally, FLT3 inhibitors may modulate BCL-XL and MCL-1 expression, increasing the dependence of tumor cells on BCL-2 and potentially enhancing the efficacy of venetoclax." (PMID 40016600, 2025). "To determine whether the greater MHC-II gene expression in CB tumors correlated with tumor or immune cells, we evaluated the dendritic cell genes ITGAX and FLT3 and the macrophage gene ITGAM, corresponding to the CD11b protein expressed on the surface of macrophages." (PMID 34548479, 2021). "Therefore, an anti-tumor antibody targeting CD52, such as alemtuzumab, is a potential therapeutic alternative for AML with FLT3-ITD, given that this antibody targets and kills leukemic cells by a mechanism that is different from that of the FLT3 kinase inhibitors." (PMID 34035227, 2021). "Quizartinib, an FLT3 inhibitor frequently mutated in AML, induces the quiescence of normal murine multipotent progenitors conferring a significant protection to mice treated with chemotherapy without affecting the elimination of FLT3-independent tumours by cytotoxic drugs." (PMID 32560371, 2020). "Exploring potential “on-target off-tumor” toxicity, we did not detect binding of our FLT3 binder 4G8 to a wide array of normal cryopreserved tissues as well as to thrombocytes, erythrocytes and granulocytes in immunohistological and flow cytometric analyses, respectively." (PMID 31817795, 2019). "Among the proteins of interest (NPM1, FLT3, DNMT3A, IDH1, IDH2, KIT, and RAS), non-mutation bearing ligands from NPM1 were the most frequent in both patient tumor samples and cell lines, including ligands close to or corresponding to where hotspot mutations occur (EAIQDLWQW and MTDQEAIQDLWQWR)." (PMID 31291378, 2019). "Notably, several multi-kinase inhibitors, including dovitinib (FLT-3/c-Kit, FGFR1/3, and VEGFR) and cediranib (VEGFR, FIT1/4, and c-KIT), showed significantly high anti-tumor activities in HGSCs (P = 2.92 × 10−02 and P = 3.98 × 10−03 for dovitinib and cediranib, respectively)." (PMID 31771620, 2019). "However, measurable immune responses and control of tumor growth were achieved only by adopting complex protocols involving adoptive transfer of antigen-specific transgenic T cells and co-administration of anti-CD40, Flt3, GMCSF and/or CpG." (PMID 21379572, 2011). "Notably, FLT3 expression was not significantly changed between tumor and normal samples." (PMID 39311766, 2024). "FLT3-ITD- bone marrow samples also had elevated levels of cDCs in the bone marrow compared to HD, but the highest observed frequencies were in the FLT3-ITD+ AML, suggesting that there are cDC precursors that are not tumor blasts that retain this mutation and expand." (PMID 38495876, 2024). "Despite the important roles of MERTK and FLT3 in immune cell development, little effort has been done to fully elucidate the effect that new generation of MERTK or FLT3 inhibitors may have on a prime component the anti-tumor immune response, namely cytotoxic CD8+ T cells." (PMID 34835225, 2021). "However, extensive mutational analysis of tumor genes could not identify predictive markers of regorafenib efficacy, including among genes involving in angiogenesis (FLT1, FLT2, FLT3, FLT4, KDR, TEK (TIE2), and VHL)." (PMID 33322802, 2020).
tumor (continued). "For instance, the pro-oncogenic FLT3-ITD mutation found in many AML patients promotes higher macroautophagy levels, suggesting that macroautophagy is not tumor-suppressive in this setting and may instead be tumor-promoting." (PMID 32245178, 2020). "Among the tumor cell lines tested, MCA205, MC38, and EMT6 lacked expression of FLT3, c-KIT, and CSF1R." (PMID 39782686, 2025). "We used two tumor cell lines, Flt3-positive THP-1-mKate2 and Flt3-negative U937-mKate2, to test the cytotoxicity and specificity of Flt3m-CAR T-cells." (PMID 37108788, 2023). "This study also showed that FAT1 exerted tumour suppressor activity specifically in FLT3‐ITD‐positive AML, perhaps providing a partial explanation for the lack of prognostic impact of FLT3‐ITD in this subpopulation." (PMID 34101344, 2021). "The observation that potentially druggable mutations, such as FLT3 ITD, are commonly lost at relapse may be interpreted as supporting the exploration of maintenance strategies which utilise drug or cellular therapies with broader anti‐tumour specificity as opposed to targeted therapies." (PMID 31823351, 2020). "In marked contrast, for the KG-1 (FLT3-WT) tumor bearing animals, AC220 treatment did not significantly inhibit tumor cell growth (TGI=5.4%)." (PMID 29682194, 2018). "Indeed, the use of Flt-3 alone had no influence on the second graft, suggesting that the effect was not due to an unspecific boost of immunity induced by the Flt-3 ligand, but rather to the amplification of a tumor-specific response induced by the tumor irradiation." (PMID 25245327, 2014). "Clinical studies have shown that treatment with a single FLT3 inhibitor does not yield therapeutic benefits in AML patients, suggesting that they may not be optimal to fully inhibit FLT3 in tumours." (PMID 22187040, 2012).
cancer (328 papers, 2007 to 2026). A tumor composed of atypical neoplastic, often pleomorphic cells that invade other tissues. "Integrating gene expression and DNA methylation analyses shed light on the impact of FLT3 mutations on cancer cell development and differentiation, supporting a two-hit model in AML." (PMID 38944027, 2025). "This suggested that CRBN(FLT3)-8 selectively targeted and inhibited the growth of cancer cells expressing the FLT3-ITD mutation." (PMID 40793752, 2025). "For this patient’s cancer, a clinically actionable FLT3-ITD mutation was identified, and DST was subsequently used to guide FLT3i selection." (PMID 38605166, 2024). "The sole actionable mutation matched to a patient’s cancer type was a FLT3-ITD mutation identified in one out of two sequenced patients with AML (50%)." (PMID 38605166, 2024). "High expression of CCR7, IL2RG, CXCL9 and MAPK10 was associated with elevated drug sensitivity of cancer cells, while high expression of FLT3 was associated with diminished drug sensitivity of cancer cells to one drug (INK-128)." (PMID 38438469, 2024). "In a recent study of NC JMD FLT3 deletion mutations, the Catalogue of Somatic Mutations in Cancer (COSMIC) database was queried for deletions observed in patients spanning FLT3 residues 572–575." (PMID 38112995, 2024). "FLT3 inhibitors can directly target the cancer cells with FLT3 mutations while epigenetic drugs can modify the epigenetic landscape of the cells, potentially enhancing the effectiveness of FLT3 inhibition." (PMID 38696033, 2024). "Mutations in the FLT3 gene lead to overactive tyrosine kinase, promoting the growth and division of cancer cells." (PMID 38671491, 2024). "For example, inducing mitophagy in AML has been most effective at destroying cancer cells that harbored FLT3-ITD mutations." (PMID 39902131, 2024). "A systematic prioritization of disease-causing SNVs identified in FLT3, a key cancer biomarker gene, and the prediction of the functional effects of missense variants using knowledge-based learning methods were attempted." (PMID 38542393, 2024). "They resensitize cancer cells through the downregulation of MCL-1 expression in the FLT3 mutated cells, resulting in the stronger efficacy of BCL-2 inhibitors." (PMID 37958832, 2023). "Obviously, the mutations in RTKs have an influential role in several cancers, especially mutations in RTK III (FLT3) that occur frequently in AML cancers." (PMID 37735675, 2023). "Most studies on the role of FLT3 in cancer focus on activating FLT3 mutations including an internal tandem duplication in AML33,34." (PMID 36697489, 2023). "As FLT3 mutations increase in AML and related carcinomas, TKIs have become a possible method of treating patients with FLT3-ITD mutations." (PMID 36605494, 2023). "Using ASOs against the FLT3‐ITD mutation can potentially provide a cancer‐specific treatment with minimal adverse effects." (PMID 35851970, 2022). "Recent studies of cancer clonal evolution have suggested that additional RAS mutations are associated with resistance to FLT3 inhibitors in FLT3-mutated AML." (PMID 35216478, 2022). "Our results confirm previous findings indicating that the inhibition of FLT3 signaling represents one of several molecular mechanisms underlying TQ-induced cancer cell growth inhibition." (PMID 34959687, 2021). "FLT3-ITD+ induces constitutive activation of FLT3, causing an abnormally rapid proliferation of cancer cells." (PMID 33167505, 2020). "The effect of STAT5 inhibitors 10, 16, and 18 on the proliferation of cancer cells carrying the common FLT3-ITD mutation after 48 h was quantified by the Alamar Blue assay." (PMID 30622248, 2019).